RNU6-898P (RNA, U6 small nuclear 898, pseudogene)
Gene: Small nuclear RNA gene on chromosome 16 (69,007,052 to 69,007,155, reverse strand). Ensembl gene ENSG00000202497.
Homologues: Orthologues: chimpanzee U6 (100% identical), macaque U6 (90% identical), dog U6 (82% identical). Paralogues in human: RNU6-24P (88% identical), RNU6-338P (88% identical), RNU6-1060P (87% identical), RNU6-1094P (87% identical), RNU6-1124P (87% identical), RNU6-11P (87% identical), RNU6-37P (87% identical), RNU6-43P (87% identical), RNU6-1117P (86% identical), RNU6-12P (86% identical), RNU6-1329P (86% identical), RNU6-13P (86% identical), and 1287 more.